MYO6 (myosin VI)
Diseases named in the same sentence as MYO6 in open-access papers (continued):
Sharing a sentence is not in itself a finding about the gene and the disease.
nonsyndromic hearing loss (3 papers, 2023 to 2024). "In roof/epithelial (CD−M1), Myo6 and Actg1 were associated with nonsyndromic hearing loss (NSHL), Hsd17b4 with Perrault syndrome, Ednrb and Edn3 with Waardenburg syndrome, and Actg1 with Baraitser–Winter syndrome." (PMID 39684410, 2024). "The other two myosin genes, MYO6 and MYO7A, depending on the variants, are associated with both autosomal dominant and recessive nonsyndromic hearing loss, respectively, as DFNA22 and DFNB37 for MYO6 and DFNA11 and DFNB2 for MYO7A." (PMID 38562617, 2024).
prostate tumor (3 papers, 2016 to 2024). "Of note, myosin VI (MYO6) is a minus-end-directed motor protein that binds AR, regulates AR stability, and modulates AR-dependent transcription in prostate tumor cells." (PMID 27365400, 2016). "We also demonstrated that MYO6 expression is upregulated in prostate tumors compared to normal tissue, and in higher Gleason grade tumors." (PMID 38673886, 2024). "It is also important to acknowledge prostate tumor heterogeneity, as profiling is not cell-specific and the miR-145-5p/MYO6 relationship may be more significant in certain cell populations." (PMID 38673886, 2024). "In addition, seven other genes, GGT1, HDAC1, KLK2, MYO6, PLA2G7, BICD1, and CACNAID, were found to be differentially expressed in prostate tumors of non-BCR and BCR patients." (PMID 31741711, 2019).
Arrhythmia (2 papers, 2021 to 2025). Any cardiac rhythm other than the normal sinus rhythm. "Studies have suggested that mutations in the MYO6 gene might be associated with arrhythmias and episodes of sudden cardiac death, indicating its involvement in the regulation of cardiac growth and function." (PMID 40687556, 2025).
breast carcinoma (2 papers, 2020 to 2023). "Other PSGs are also of interesting; for instance, Myosin‐6 (MYO6, likelihood ratio test (LRT) p value = 6.67 × 10−11) is significantly upregulated in prostate and breast cancer." (PMID 37395176, 2023).
Parkinson disease (2 papers, 2020). A progressive degenerative disorder of the central nervous system characterized by loss of dopamine producing neurons in the substantia nigra and the presence of Lewy bodies in the substantia nigra and locus coeruleus. "In addition, circMap1a also interacts with the mRNAs of Myo6, which is required for BDNF-mediated neurotransmission and Park7, associated to Parkinson’s Disease and encoding a DJ-1 protein protecting brain cells from oxidative stress." (PMID 32849796, 2020).
sensorineural hearing loss (2 papers, 2023 to 2024). "Many mutations of human MYO6 gene lead to sensorineural hearing loss (SNHL) with no effective treatment." (PMID 36849547, 2023).
Stroke (2 papers, 2022 to 2024). Sudden impairment of blood flow to a part of the brain due to occlusion or rupture of an artery to the brain. "Myosin VI has a unique insert in its lever arm that reverses stroke direction and makes it the only known minus end–directed actin-based motor." (PMID 35143838, 2022). "List of collective variables defined in the study of the myosin VI recovery stroke." (PMID 38662764, 2024).
age-related macular degeneration (1 paper, 2015). Age-related loss of vision in the central portion of the retina (macula), secondary to retinal degeneration. "The depletion of myosin VI leads to a visual phenotype that may recapitulate functional and morphological characteristics of glaucoma as well as age-related macular degeneration (AMD) pathology." (PMID 25939269, 2015). "A phenotype comprising features of glaucoma (neurodegeneration) and age-related macular degeneration could thus be uncovered that suggests dysfunction of myosin VI and its variable cargo adaptor proteins for membrane sorting and autophagy, as possible candidate mediators for both disease forms." (PMID 25939269, 2015).
allergic asthma (1 paper, 2015). A asthma with a basis in a pathological type I hypersensitivity reaction. "Furthermore, the upregulated genes (PDPK1, EZR, MYO6, CDC42BPA, OPHN1, ARF6 and WASL) identified in the present study that were enriched in the actin filament-based process require further study in order to determine whether they may be used as potential biomarkers of allergic asthma." (PMID 25633562, 2015).
artery disease (1 paper, 2023). "Additionally, we identified MYO6 as LVOTO genes that was previously reported to be associated with artery disease." (PMID 38164514, 2023).
breast tumors (1 paper, 2020). "Amongst these were 4 extensively studied splicing isoforms (MYO6, TPD52, IQCG, and ACOX2) identified to be amongst the 5 most important isoforms differentially expressed between ER+HER2− and ER-HER2 primary breast tumors." (PMID 33050927, 2020).
cervical cancer (1 paper, 2021). A primary or metastatic malignant neoplasm involving the cervix. "In this regard, LMTK2 is known to bind directly to myosin VI in human cervical cancer HeLa cells, permitting the delivery of membrane pumps, channels, and nutrient receptors from the early endosome to the perinuclear endocytic recycling compartment (ERC) and to the plasma membrane." (PMID 34064250, 2021).
clear cell renal cell carcinoma (1 paper, 2025). "MYO6 knockdown is associated with disease progression, poor prognosis and immune cell infiltration in clear cell renal cell carcinoma." (PMID 41262242, 2025).
cyst (1 paper, 2009). A sac-like closed membranous structure that may be empty or contain fluid or amorphous material. "We found that both myosin VII (ck) and myosin VI (jar) were present in punctate spots in the head cyst cell cytoplasm (arrows) and jar/myosin VI was enriched along the actin cap extensions (arrowheads)." (PMID 19416498, 2009).
endometriosis (1 paper, 2023). The growth of functional endometrial tissue in anatomic sites outside the uterine body. "The difference in the results of dataset GSE7305 demonstrated that all NRDEGs were statistically significant, and the expression levels of C7, HOOK1, PKP3, AHR, GJB1, and MYO6 in different groups of endometriosis dataset GSE7305 were statistically significant (P < 0.001)." (PMID 37817158, 2023). "Our findings suggest that MYO6 and HOOK1 are associated with immune infiltration in endometriosis and can be used as novel potential biomarkers and predictors of immune cell infiltration in endometriosis." (PMID 37817158, 2023). "The immunohistochemical result indicated that the protein levels of MYO6 and HOOK1 were increased in patients with endometriosis, further suggesting that MYO6 and HOOK1 can be used as potential biomarkers for endometriosis." (PMID 37817158, 2023). "MYO6 and HOOK1 can be used as potential biomarkers for endometriosis." (PMID 37817158, 2023). "MYO6 and HOOK1 have a limited impact on the immune system in endometriosis." (PMID 37817158, 2023).
glaucoma (1 paper, 2015). Increased pressure in the eyeball due to obstruction of the outflow of aqueous humor. "Taken together, the present study not only introduces myosin VI as a gene potentially responsible for genetic predispositions of either AMD or glaucoma." (PMID 25939269, 2015). "Thus, this study suggests that disturbance of the myosin VI-mediated membrane cycle process may be a potential risk factor for the generation of AMD, glaucoma, or the described co-morbidity of both." (PMID 25939269, 2015).
glioma (1 paper, 2013). A benign or malignant brain and spinal cord tumor that arises from glial cells (astrocytes, oligodendrocytes, ependymal cells). "In C6 glioma cells, however, introduction of Myo6 siRNA induced a drastic decrease in endogenous Myo6 protein levels without significantly affecting MTT reduction." (PMID 23691122, 2013). "In C6 glioma cells cultured for 2 days, marked expression of Myo6 protein was seen in a manner sensitive to knockdown by siRNA." (PMID 23691122, 2013). "Although MTT reduction gradually increased in C6 glioma cells treated with control siRNA during increasing culture periods up to 4 days, Myo6 siRNA failed to significantly affect MTT reduction during the 4 days." (PMID 23691122, 2013). "The Ca2+ ionophore A23187 drastically increased the luciferase activity in P19 cells transfected with a Myo6 promoter reporter plasmid, but not in HEK293, Neuro2A and C6 glioma cells transfected with the same reporter." (PMID 23691122, 2013).
heart failure (1 paper, 2025). Inability of the heart to pump blood at an adequate rate to meet tissue metabolic requirements. "The effects of AR-DS on cardiac autophagy status in heart failure rats through the MYO6-Tom1 complex were further explored to elucidate the mechanism of its action." (PMID 40687556, 2025). "AR-DS exerts a protective effect on myocardial tissue in heart failure rats by inhibiting myocardial autophagy, potentially through the modulation of the MYO6-Tom1 complex." (PMID 40687556, 2025). "In summary, our study has for the first time demonstrated that the potential mechanism by which AR-DS treats heart failure may involve the inhibition of myocardial autophagy through the MYO6-Tom1 complex." (PMID 40687556, 2025). "Therefore, AR-DS may inhibit heart failure in rats by blocking the formation of the MYO6-Tom1 complex in the myocardium, thereby impeding the fusion of autophagosomes with lysosomes and reducing myocardial autophagy, ultimately improving cardiac function in heart failure rats." (PMID 40687556, 2025).
Intellectual disability (1 paper, 2013). "In previous studies, 6q14, containing the genes MYO6 and SEN6, has been associated with intellectual disability and language delay." (PMID 23460800, 2013).
ischemia (1 paper, 2017). A hypoperfusion of the BLOOD through an organ or tissue caused by a PATHOLOGIC CONSTRICTION or obstruction of its BLOOD VESSELS, or an absence of BLOOD CIRCULATION. "Mice lacking myosin VI had a modest reduction in the GJ intercalated disc size in their hearts, so it will be interesting to assess the maintenance of Cx43 homeostasis, including Cx43 accretion rates into GJs, in response to pathological insults such as ischemia and chronic elevations in afterload." (PMID 28096472, 2017).
lymphoma (1 paper, 2023). A malignant (clonal) proliferation of B- lymphocytes or T- lymphocytes which involves the lymph nodes, bone marrow and/or extranodal sites. "While further studies are needed to investigate MYO6 regulation of lymphoma cell dynamics and to design novel therapeutic approaches, a monoclonal antibody targeting the neoepitope generated by mutated CALR in myeloproliferative disorders has been generated." (PMID 38035116, 2023).
male infertility (1 paper, 2020). The inability of the male to effect fertilization of an ovum after a specified period of unprotected intercourse. "It must be noted, however, that in contrast to Drosophila in which the lack of MYO6 expression leads to male infertility, in MYO6-deficient mice, the phenotype is less pronounced." (PMID 31901088, 2020). "The lack of MYO6 in developing Drosophila spermatids leads to the disturbed distribution of these ABPs and abnormal structure of actin cones, and as a result, to male infertility." (PMID 31901088, 2020).
melanoma (1 paper, 2020). A malignant, usually aggressive tumor composed of atypical, neoplastic melanocytes. "In melanoma, knockdown of myosin VI significantly suppressed cell viability and proliferation, and induced cell cycle arrest in G0/G1 phase, confirming the role of myosin VI in tumor progression." (PMID 33171868, 2020).
metastatic tumors (1 paper, 2020). "In PCa, Myo1b, Myo6, Myo9b, Myo10, and Myo18a were expressed at higher levels in high metastatic potential cells, and especially Myo1b and Myo10 were expressed at higher levels in metastatic tumors." (PMID 33292248, 2020).
Pick disease (1 paper, 2019). A rare neurodegenerative disorder leading to dementia. "The authors went on to report that Myosin VI associated with Tau tangles in a small number of brains from AD and FTDP-17 cases but not from individuals with a postmortem diagnosis of PSP or Pick’s disease." (PMID 31700063, 2019).
presbycusis (1 paper, 2014). Bilateral hearing loss caused by progressive degeneration of cochlear structures and central auditory pathways, typically associated with the aging process. "Hearing loss in the family closely resembled presbycusis and the authors hypothesized that rare variants of MYO6 may contribute to presbycusis." (PMID 25140308, 2014).
prostatic adenocarcinoma (1 paper, 2010). "The immunoexpression of myosin VI has been demonstrated in prostatic adenocarcinoma." (PMID 20074327, 2010).
retinal degeneration (1 paper, 2015). Degeneration of the retina. "However, compared to other hereditary retinal degeneration models, the cell death rate in myosin VI-deficient mice is rather low, which may correspond to the very protracted degeneration process in human AMD." (PMID 25939269, 2015).
Salmonella Infections (1 paper, 2015). Infections with bacteria of the genus SALMONELLA. "To compare the function of myosin VI and the autophagy receptors in controlling Salmonella infection, we utilised a Gentamicin protection assay to measure Salmonella proliferation within the cytosol." (PMID 26451915, 2015).
trypanosomiasis (1 paper, 2024). Infection with protozoa of the genus trypanosoma. "Additionally, genes such as SENP6 and MYO6, associated with apoptosis and cellular transport, may contribute to the breed’s resilience against diseases like trypanosomiasis, common in their geographic area." (PMID 39119582, 2024).
cancer (27 papers, 2008 to 2025). A tumor composed of atypical neoplastic, often pleomorphic cells that invade other tissues. "High expression of MYO6 (myosin VI) has been associated with tumour progression in multiple cancers, including prostate, CRC, breast and stomach." (PMID 32878019, 2020). "This can impact on myosin VI function in health and disease, as it has been proposed to be case in cancer, where the loss of Dab2 enhances myosin VI–mediated transcription." (PMID 31861842, 2019). "Some somatic mutations in GIPCs found in human cancer also map to structural elements that are important for the protein stability or the interaction with myosin VI." (PMID 28537552, 2017). "The loss of miR-145-5p expression may therefore promote cancer progression through disinhibition of MYO6 and subsequent induction of EMT." (PMID 38673886, 2024). "Targeting MYO6 has been proposed by others as a potential therapeutic approach in gastric and breast cancers to suppress tumor proliferation and metastasis." (PMID 38673886, 2024). "miR-145 binds to the 3′UTR of MYO6 and is regulated inversely, resulting in a decrease in myosin VI; which, is involved in cancer-related cell migration and β-actin in the LNCaP PCa cell line." (PMID 37190259, 2023). "MYO6 is necessary for collective cell migration related to tumor progression and spread of certain cancers." (PMID 32670437, 2020). "The miR-145 binds to the 3'UTR of MYO6 gene and regulated negatively, resulting in a decrease in myosin VI (involved in cancer-related cell migration), and β-actin in LNCaP cell line." (PMID 28320379, 2017). "The increasing expression level of GOLPH2 and myosin VI indicates Golgi-specific alterations related to the molecular composition in cancer cells." (PMID 27121062, 2016). "The border cell migration mediated by myosin VI has served as a useful paradigm for cancer cell invasion." (PMID 27121062, 2016). "Identifying the role of myosin VI in cell migration has acquired greater urgency with the discovery that myosin VI is involved in cancer cell invasion." (PMID 18068125, 2008). "So far the best example for myosin VI’s role in cell motility is in border cell migration in Drosophila ovaries, which has served as a model for cancer cell invasion." (PMID 18068125, 2008). "The function of MYO6 in cancer was subsequently explored via in vitro experiments." (PMID 41262242, 2025). "Research has indicated that non-coding RNA (miRNA) has the ability to impact the growth and advancement of tumors by controlling the expression of MYO6.In NSCLC cells, miR-5195-3p functions as a cancer inhibitor through the direct regulation of MYO6 expression." (PMID 37965333, 2023). "In this context, it is worth mentioning that myosin VI is an early marker of tumorigenesis, aggressiveness, and invasion since it is dramatically up-regulated in various cancer cells including RCC44 and maybe also breast cancer cells." (PMID 37666879, 2023). "In addition to stimulating cancer cell proliferation, MYO6 promotes migration and invasion of various cancer cells by mechanisms that remain to be identified." (PMID 33670106, 2021). "MYO6 was an oncogene, which had been demonstrated in diverse cancers." (PMID 34645476, 2021). "MYO6 may regulate the metastasis of cancer cells through its effect on protein transport to the cell surface, hence affecting cell migration." (PMID 32670437, 2020). "MYO6 was overexpressed in various cancers, which suggested that it could be used as a biomarker for cancer treatment." (PMID 32993655, 2020).
cancer (continued). "It was reported that MYO6 was related to contribute to the development of human cancers." (PMID 32993655, 2020). "Our observation that MYO6 plays a role in AKT signaling is an important finding that may have wider implications for the role of MYO6 in cancer cells, since this motor is dramatically overexpressed in prostate and ovarian cancers." (PMID 28591580, 2017). "Furthermore, MYO6 is upregulated in numerous cancers, where it has been suggested to promote cell migration and invasion and thus represents a potential therapeutic target." (PMID 28591580, 2017). "Suppressing myosin VI expression prevents cancer cell invasion and migration." (PMID 27121062, 2016). "Additionally, these findings can have significant implications for the biology of α5β1-expressing human carcinomas, in which Myo6 can be overexpressed and promote metastatic invasion." (PMID 19175293, 2009). "When A431 (a human epithelial carcinoma cell line) cells are stimulated with epidermal growth factor (EGF) myosin VI is recruited into the dynamic ruffling membrane at the leading edge and there is a four-fold increase in the level of myosin VI phosphorylation." (PMID 18068125, 2008). "Similarly, the expression levels of both miR-145-5p and MYO6 in tumor tissue is significantly correlated with survival outcomes in several other TCGA patient cohorts, indicating that they could together be useful prognostic biomarkers for different cancers." (PMID 38673886, 2024). "Here, we dissect the multimodal regulation of myosin VI activity through the cargo adaptor GAIP-interacting protein, C terminus (GIPC), whose overexpression with this motor in cancer enhances cell migration." (PMID 35143838, 2022). "Furthermore, cell-growth promotion by MYO6 is associated with its known interactions with RNA polymerase II in the nucleus and stimulation of mRNA transcription, although the causal connection of this mechanism to cancer growth has not been investigated." (PMID 33670106, 2021). "The finding that overexpression of ZNF191 significantly down-regulated BMPR2, PDGFR and MYO6, whereas silencing of ZNF191 increased BMPR2, PDGFR and MYO6 expression suggests a tumor suppressor role for ZNF191 in human cancers." (PMID 19463170, 2009). "Interestingly, myosin VI has been correlatively shown to be overexpressed in the same cancers as GIPC, and downregulation of both GIPC and myosin VI was shown to ameliorate the cancerous phenotype." (PMID 35143838, 2022).